CPLX3 (complexin 3)
Description:
Complexin that regulates SNARE protein complex-mediated synaptic vesicle fusion (By similarity). Required for the maintenance of synaptic ultrastructure in the adult retina (By similarity). Positively regulates synaptic transmission through synaptic vesicle availability and exocytosis of neurotransmitters at photoreceptor ribbon synapses in the retina (By similarity). Suppresses tonic photoreceptor activity and baseline 'noise' by suppression of Ca(2+) vesicle tonic release and the facilitation of evoked synchronous and asynchronous Ca(2+) vesicle release (By similarity).
Synonyms: Nbla11589; CPX-III; CPXIII
Tractability: Antibody: UniProt places it where antibodies can reach, with medium confidence; its Gene Ontology location is reachable by antibodies, with medium confidence. PROTAC: its protein half-life has been measured.
Gene: Protein-coding gene on chromosome 15 (74,826,627 to 74,831,802, forward strand). Ensembl gene ENSG00000213578.
Subcellular location: Synapse; Cell membrane
Gene Ontology:
Molecular function: SNARE binding; neurotransmitter transmembrane transporter activity
Biological process: modulation of chemical synaptic transmission; regulation of synaptic vesicle fusion to presynaptic active zone membrane; synaptic vesicle exocytosis; insulin secretion; neurotransmitter transport
Cellular component: SNARE complex; synapse; terminal bouton; cytosol; membrane; photoreceptor ribbon synapse; plasma membrane; presynaptic active zone membrane; synaptic vesicle membrane
Genetic constraint (gnomAD): Loss-of-function variants: 12 observed, 16.33 expected, observed/expected ratio (o/e) 0.73, 90% interval 0.47 to 1.19. The upper end of that interval is the gene's LOEUF score, 1.19, which puts it in group 5 of 6, group 1 being the genes least tolerant of losing a copy. Missense variants: 172 observed, 207.37 expected, observed/expected ratio (o/e) 0.83, 90% interval 0.73 to 0.94. Synonymous variants: 75 observed, 81.03 expected, observed/expected ratio (o/e) 0.93, 90% interval 0.77 to 1.12.
Homologues: Orthologues: chimpanzee CPLX3 (99% identical), macaque CPLX3 (99% identical), pig CPLX3 (98% identical), dog CPLX3 (97% identical), guinea pig CPLX3 (96% identical), mouse Cplx3 (96% identical), rat Cplx3 (96% identical), tropical clawed frog lman1l (80% identical), zebrafish cplx3b (68% identical), rabbit CPLX3 (68% identical), zebrafish CPLX3 (64% identical), zebrafish cplx3a (64% identical), and 3 more. Paralogues in human: CPLX4 (61% identical), CPLX2 (28% identical), CPLX1 (27% identical).
Diseases named in the same sentence as CPLX3 in open-access papers:
CPLX3 is named in the same sentence as 7 diseases in open-access papers, as found by Europe PMC text mining. Sharing a sentence is not in itself a finding about the gene and the disease. The quoted sentences say what the papers report.
lentivirus infection (1 paper, 2024). Virus diseases caused by the Lentivirus genus. "Hence, it is intrinsically difficult to analyze Complexin 3 levels, and lentivirus infection increased Complexin 3 levels." (PMID 38932933, 2024).
schizophrenia (1 paper, 2020). A major psychotic disorder characterized by abnormalities in the perception or expression of reality. "In this point of view, the reduction of Cplx3-positive layer VIb neurons might affect the processing of sensory information in Disc1 Het mice which might model the sensory processing deficiency in patients with schizophrenia." (PMID 33384588, 2020).
viral infection (1 paper, 2024). "While Complexin 3 is normally not detectable in neuron cultures, it becomes detectable upon viral infection." (PMID 38932933, 2024).
tumor (1 paper, 2021). "The upregulated genes CPLX3 and SPAG6 appeared to be associated with poor survival, whereas the downregulated genes GDPD5, NXPH1, and AHI1 were identified as tumor suppressors." (PMID 34950701, 2021). "The downregulated genes GDPD5, NXPH1, and AHI1 were identified as tumor suppressors, while the upregulated genes CPLX3 and SPAG6 were regarded as oncogenes." (PMID 34950701, 2021).
CPLX3 also shares sentences with these, for which no sentence is quoted: Anxiety (1 paper); attention deficit-hyperactivity disorder (1); COVID-19 (1).